USP13 (ubiquitin specific peptidase 13)
Diseases named in the same sentence as USP13 in open-access papers (continued):
Sharing a sentence is not in itself a finding about the gene and the disease.
tumor (50 papers, 2012 to 2026). "Single-cell RNA sequencing analysis indicated that high expression of USP13 in HCC cells was associated with decreased enrichment of CD8 + T cells in the tumor microenvironment (TME)." (PMID 41330897, 2025). "In both colony formation assays and xenograft models, the impaired tumor growth caused by USP13 knockout was effectively rescued by MYC-p38α overexpression." (PMID 41307804, 2025). "As a deubiquitinase enzyme, USP13 has been implicated in tumor promotion or suppression by regulating the stability of various substrate proteins via deubiquitination processes." (PMID 38093367, 2023). "The reduced volume and weight of tumor nodules caused by USP13 silence was found to be counteracted by ectopic overexpression of METTL3 in 143B cells." (PMID 37151889, 2023). "In this study, we found that the deubiquitinase USP13 is highly expressed in SCLC tumor samples and positively associated with poor prognosis in multiple cohorts." (PMID 35898882, 2022). "Through anticipating neddylation process, USP13 potentially enhanced the activities of CAFs, CAEs and tumor-associated macrophages (TAMs), thereby promoting angiogenesis and tumor metastasis." (PMID 36564767, 2022). "The positive expression of USP13 was significantly associated with tumor size ≥ 5 cm (P = 0.003) and advanced tumor-node-metastasis (TNM) stage (III + IV, P = 0.024), as analyzed by chi-square test." (PMID 33195243, 2020). "The loss of USP13 results in enhanced Akt phosphorylation and tumor growth." (PMID 39678489, 2024). "Based on these findings, it appears that overexpression of USP13 causes an increase in MYC protein during the initial stages of tumor development originating from club cells, which may contribute to the development of LUSC." (PMID 38093367, 2023). "Notably, the positive expression of USP13 was associated with unfavorable clinical features, such as tumor size ≥ 5 cm and advanced TNM stage (III + IV), and indicated poor prognosis of HCC patients." (PMID 33195243, 2020). "However, USP13 deficiency conferred tumours hypersensitive to Olaparib treatment in a xenograft model." (PMID 28569838, 2017). "Although the experimental results showed that USP13-UBA could bind ubiquitin, USP13 still exhibited only weak deubiquitination enzyme activity, which is incompatible with the findings that USP13 can deubiquitinate various important substrates implicated in disease and tumor development." (PMID 35445009, 2022). "Future studies with larger clinical cohorts, diverse CRC models, and multi-omics approaches are warranted to validate these findings and elucidate the broader regulatory network of USP13 in tumor angiogenesis." (PMID 40746889, 2025). "Nanjing medical university investigated the function of USP13 in HCC, they found that USP13 was significantly upregulated in both of primary HCC tumor tissues and cell lines." (PMID 40607251, 2025). "Tumor tissues from patients with high USP13 expression exhibited significantly lower CD31 expression as compared to those with low USP13 expression." (PMID 40746889, 2025). "Ubiquitin-specific peptidase 13 (USP13) is a deubiquitinating enzyme with a pivotal effect on tumor proliferation, metastasis, and tumorigenesis." (PMID 40746889, 2025). "In vivo experiments further confirmed that silencing USP13 led to a significant reduction in tumor size, accompanied by an increase in both CD8 + T cell infiltration and the expression levels of GZMB and IFN-γ within the tumor tissue." (PMID 41330897, 2025). "USP13 overexpression remarkably decreased tumor volume and weight as compared with those in the EV group." (PMID 40746889, 2025). "Our research found that treatment with 2-Met or deletion of USP13 in tumor cells led to significantly increased CD8 + T cell infiltration, along with elevated GZMB and IFN-γ secretion, indicating enhanced T cell activity." (PMID 41330897, 2025).
tumor (continued). "Tumors from Usp13−/− mice exhibited significantly impaired growth, as assessed by reduced growth rate, tumor volume, and weight compared to wild-type controls." (PMID 41307804, 2025). "We observed that exogenously expressed ACLY reversed the anti-tumor effects induced by USP13 depletion." (PMID 41330897, 2025). "2-Methoxyestradiol (2-Met), an inhibitor of USP13 from a natural compound library, has been shown to exhibit promising anti-tumor effects in some cancers." (PMID 41330897, 2025). "USP10 and USP13 can mediate the deubiquitination of the autophagy-related protein Beclin1, stabilizing Beclin1 levels and exerting a tumor-suppressive effect." (PMID 40083330, 2025). "Recent studies have explored the role of USP13 in modulating the tumor immune microenvironment, highlighting its influence on immune evasion mechanisms, such as regulating immune checkpoint pathways and immune cell activity." (PMID 41330897, 2025). "Combining USP13 inhibitors with existing immunotherapies, such as PD-1/PD-L1 inhibitors, represents a promising strategy to improve anti-tumor efficacy." (PMID 41330897, 2025). "Molecular mechanisms were analyzed via Western blot (PTEN, p-AKT, VEGFA), co-immunoprecipitation (PTEN ubiquitination), and in vivo nude mice study to detect the role of USP13 in tumor angiogenesis." (PMID 40746889, 2025). "Conversely, overexpression of USP13 using AAV8-USP13 in mice produced the opposite effects: tumor volume significantly increased, AFP levels were elevated, and the infiltration of CD8 + T cells was notably reduced." (PMID 41330897, 2025). "This indicated that USP13 fosters a tumor-supportive microenvironment in vivo, and its knockout consequently compromises tumor cell colonization and proliferation." (PMID 41307804, 2025). "USP13 also inhibited tumor angiogenesis through downregulating VEGFA, and recombinant VEGFA blocked the inhibition of the conditioned medium from USP13-overexpressing CRC cells against HUVEC angiogenesis in vivo." (PMID 40746889, 2025). "Given the involvement of several cytokines and growth factors related to tumor angiogenesis, this study investigated if USP13 affects the production of essential cytokines that promote angiogenesis." (PMID 40746889, 2025). "m6A-modified USP13 induces autophagy and imatinib resistance in gastrointestinal stromal tumor cells by regulating ATG5 stability." (PMID 40781108, 2025). "We elucidate a novel molecular mechanism whereby USP13 stabilizes MKK3 by removing its K48-linked ubiquitination, thereby enhancing p38 activation and driving tumor malignancy." (PMID 41307804, 2025). "Inhibition of USP13 significantly suppressed tumor progression and sensitized tumor cells to PI3K/AKT inhibitors." (PMID 40746599, 2025). "USP13 was shown to positively promote glycolysis and tumor progression by stabilizing and deubiquitinating METTL3, which is a well-known “writer” for m6A modification, at K488 by removing K48-linked ubiquitin chains." (PMID 37151889, 2023). "PTEN is deubiquitinated by USP13 in bladder cancer, and its stabilized expression suppresses tumor progression." (PMID 37497216, 2023). "Ubiquitin-specific peptidase 13 (USP13) is overexpressed in HCC and, notably, is associated with a tumor burden greater than 5 cm, as well as advanced tumor-node-metastasis (TNM) stages (III and IV)." (PMID 37345131, 2023). "Nude mouse experiments indicated that depletion of USP13 in GC cells dramatically suppressed tumor growth in vivo." (PMID 37311811, 2023). "We further demonstrated that USP13 obviously promoted OS cells invasion using a 3D tumor spheroid cell-invasion assay." (PMID 37151889, 2023). "The upregulation of USP13 in OS tissues was further validated by western blotting in twelve randomly-selected pairs of tumor tissues and corresponding adjacent normal tissues." (PMID 37151889, 2023).
tumor (continued). "Data showed that USP13 was markedly upregulated in tumor specimens compared with adjacent normal tissues." (PMID 37151889, 2023). "Conversely, USP13 acts as a tumor suppressor by stabilizing PTEN (phosphatase and tensin homolog) in oral squamous cell carcinoma, breast cancer, and bladder cancer." (PMID 38093367, 2023). "USP13 serves as a critical regulator of tumorigenesis by inhibiting tumor growth in vivo and suppressing lactate production, glucose uptake, and cell proliferation in vitro." (PMID 37353812, 2023). "Using various in vitro and in vivo functional experiments, USP13 was demonstrated to promote glycolysis and tumor progression in OS." (PMID 37151889, 2023). "Collectively, our study results indicate that USP13 promotes glycolysis and tumor progression in OS by stabilizing METTL3, thereby stabilizing ATG5 mRNA and facilitating autophagy in OS." (PMID 37151889, 2023). "Consistently, knockdown or pharmacological inhibition of USP13 by spautin-1 retards the growth, differentiation and invasion of many tumors, providing a possibility for antagonizing the drug resistance of tumor cells." (PMID 35445009, 2022). "In conclusion, inhibition of the deubiquitination activity of USP13 can impair the energy metabolism of tumor cells, hence providing novel insights into interventions of tumor cells targeting on energy metabolism pathway." (PMID 35445009, 2022). "Protein expression of USP13 was found to be positively correlated with tumor progression of PAAD (G), HNSC (H), ccRCC (I) and UCEC (J)." (PMID 36564767, 2022). "B. Expression of USP13 was analyzed between normal and tumor tissues in 33 types of human cancers based on TCGA integrated with GTEx." (PMID 36564767, 2022). "Consistent with previous result, USP13 depletion dramatically suppressed tumor growth, and forced overexpression of WT HA-rUSP13 rescued the decreased tumor volume." (PMID 35898882, 2022). "Taken together, our study revealed a key role of USP13 in contributing to PCa progression by participating in multiple oncogenic signaling pathways, the DNA damage response and the immunosuppressive tumor microenvironment." (PMID 36564767, 2022). "We further explored USP13 expression in 33 types of human cancers based on the RNA sequencing data of normal tissues from the GTEx database along with the data of normal and tumor tissues from the TCGA database." (PMID 36564767, 2022). "The results showed that USP13 expression was significantly elevated in tumor tissues in 10 cancer types compared with normal tissue samples." (PMID 36564767, 2022). "We further analyzed the significance of USP13 expression in prostate progression, and the results confirmed that high expression of USP13 was correlated with a high Gleason’s score (8 &9 &10 vs 6 & 7) and advanced tumor stage (T3 & T4 vs T2) of PCa." (PMID 36564767, 2022). "The clusters of cell types in PCa tumor microenvironment and expression of USP13 in different cell types were analyzed in scRNA-seq profiles from GSE137829, GSE141445, GSE143791, GSE150692 and GSE172301." (PMID 36564767, 2022). "The results suggested that USP13 was differentially expressed between tumor and normal tissues in 15 cancer types; among them, USP13 was found to be significantly upregulated in tumors in 10 types of cancers." (PMID 36564767, 2022). "Overall, USP13 was found to be a potential modulator in immune cell infiltration and the tumor microenvironment modulation in PCa." (PMID 36564767, 2022). "A. USP13 was highly expressed in 496 PCa tumor tissues compared to 152 normal tissues based on TCGA and GTEx databases." (PMID 36564767, 2022). "As expected, USP13 knockout evidently inhibited tumor cell growth either in OVCA cells or xenograft tumor models in nonobese diabetic/severe combined immunodeficiency (NOD/SCID) mice." (PMID 35445009, 2022). "Next, we analyzed the proteomic expression of USP13 in cancers using data from the Clinical Proteomic Tumor Analysis Consortium (CPTAC) by UALCAN." (PMID 36564767, 2022).
tumor (continued). "Consistently, knockout or pharmacological inhibition of USP13 impeded tumor cell proliferation and enhanced sensitivity to chemotherapeutic agents in both cell lines and mouse models." (PMID 35445009, 2022). "USP13, as an important deubiquitinase member belongs to USPs subfamilies, has been revealed as a potential therapeutic target for its significant role in tumor progression." (PMID 35898882, 2022). "Using the TIMER tool, USP13 expression was analyzed and compared in 17 cancer types between tumor tissues and relative normal tissue samples." (PMID 36564767, 2022). "Last, to further examine the clinical significance of USP13, it is of great value to analyze the effects of small molecular inhibitors against USP13, such as spauntin-1, on tumor formation and growth in in vitro and in vivo PCa models." (PMID 36564767, 2022). "Mechanistically, USP13 promoted the energy metabolism of tumor cells, and provided precursor substances for the synthesis of sugar, lipids and non-essential amino acids in cancer cells, through deubiquitinating and stabilizing ACLY and OGDH." (PMID 35445009, 2022). "Deubiquitinases USP9X, Ku70, JOSD1, DUB3/USP17L2, and USP13 have been described to stabilize Mcl-1, promote tumor cell survival and suppress apoptosis." (PMID 35301297, 2022). "A growing number of studies have demonstrated that USP13 overexpression is closely related to tumor grade, tumor invasion, chemotherapy resistance and poor prognosis." (PMID 35445009, 2022). "Although USP13 plays vital role in tumor progression and drug resistance in NSCLC, its precisely biological functions and the regulatory mechanisms in SCLC remain undiscovered." (PMID 35898882, 2022). "Several substrates for USP13 have recently been identified; however, due to this, the function of USP13 in tumourigenesis is controversial, as it has been shown to regulate the expression of both tumour suppressors and oncogenes." (PMID 33627786, 2021). "Our data and TCGA data consistently revealed the upregulated expression of USP13 in HCC tissues compared to non-tumor liver tissues in the current study." (PMID 33195243, 2020). "In this study, we explored the clinical significance of USP13 in HCC and investigated the biological role of USP13 in tumor growth and metastasis in vitro and in vivo." (PMID 33195243, 2020). "Here, quantitative real-time PCR (qRT-PCR) and immunohistochemistry analysis revealed that USP13 expression in HCC tissues was higher than in non-tumor liver tissues." (PMID 33195243, 2020). "The growth curves of subcutaneous tumors formed by Hep3B cells suggested that USP13 silencing inhibited tumor growth in mice (P < 0.05)." (PMID 33195243, 2020). "In conclusion, the present study demonstrates the tumor suppressor role of USP13 in BC and the potential regulatory loop network of NF-kB/USP13/PTEN." (PMID 31200745, 2019). "Among them, we focused our attention on USP13 because of its potential role as a tumor suppressor by sustaining PTEN protein stability." (PMID 31200745, 2019). "USP10 and USP13 are critical in the development of several cancers because they regulate some key tumor promoters or suppressors." (PMID 30975171, 2019). "Here, the authors show that MCL1’s stability is regulated by deubiquitinase USP13, and its inhibition sensitises tumor cells to BH3 mimetic inhibitors." (PMID 29335437, 2018). "As a result, USP13 depletion using CRISPR/Cas9 nuclease system inhibits tumor growth in xenografted nude mice." (PMID 29335437, 2018). "Specifically, we observed a fivefold decrease in the tumor volume of USP13-depleted SW-1573 cells and a complete eradication of tumors formed by USP13-null TOV-21G cells." (PMID 29335437, 2018). "Administration of mice with Dox (2.0 mg ml−1) in drinking water markedly decreased the growth of xenograft tumours derived from the USP13-KD CAOV3 cells." (PMID 27892457, 2016).
tumor (continued). "Mice bearing CAOV3-derived tumours expressing Dox-inducible USP13 shRNA were randomly divided into four groups (Dox-untreated, Dox-treated, Dox-untreated+MK-2206 and Dox-treated+MK-2206)." (PMID 27892457, 2016). "Treatment of MK-2206 significantly inhibited the activity of AKT (indicated by pAKT levels) in both control and USP13-KD tumours." (PMID 27892457, 2016). "Examination of end-point tumour burden in Dox-treated or -untreated groups (n=10 per group) demonstrated that depletion of USP13 resulted in profound decreases in tumour weight (78.5% reduction, P<0.001) and number of nodules (68.7% reduction, P<0.001)." (PMID 27892457, 2016). "Similar to Beclin 1 knockdown, we found that suppression of the ubiquitin-specific peptidase, USP10, or a small molecule inhibitor of the deubiquitinases USP10 and USP13, i.e., spautin-1, can increase radiation-induced DSBs and promote tumor cell death." (PMID 24956373, 2014). "Recent studies highlight USP13’s critical role in tumor progression." (PMID 40370434, 2025). "Additionally, in vivo experiments using a xenograft mouse model revealed that inhibition of USP13 notably reduced tumor growth, while increasing CD8 + T cell infiltration and boosting GZMB and IFN-γ secretion in tumor tissues, thus enhancing T cell activity." (PMID 41330897, 2025). "USP13 was analyzed for its effect on tumor angiogenesis of CRC in vivo." (PMID 40746889, 2025). "Moreover, PTEN inhibitors mitigated USP13 overexpression-mediated decrease in tumor volume and weight." (PMID 40746889, 2025). "Targeting USP13 could potentially inhibit tumor growth and enhance the effectiveness of immunotherapy." (PMID 41330897, 2025). "Furthermore, this suppressive effect was profoundly enhanced by the additional knockout of USP13, leading to the greatest reduction in tumor size." (PMID 41307804, 2025). "Importantly, in vivo xenograft experiments confirmed that USP13-driven tumor growth depends on MKK3 and can be rescued by constitutive p38 activation." (PMID 41307804, 2025). "Specific USP13 knockdown in tumor cells can inhibit tumor growth, suggesting that USP13 inhibitors may have therapeutic effects on ccRCC102." (PMID 40225869, 2025). "Considering USP13’s involvement in tumor cholesterol regulation, we investigated whether its effects on T cell function and infiltration depend on cholesterol." (PMID 41330897, 2025). "Considering USP13’s involvement in tumor cholesterol regulation, we investigated whether its effects on T cell function and exhaustion depend on cholesterol." (PMID 41330897, 2025). "We explored the anti-tumor effect of 2-Met, an inhibitor of USP13 from a natural compound library." (PMID 41330897, 2025). "Similarly, USP13 interacts with and stabilizes Mcl‐1, and its inhibition reduces Mcl‐1 levels, increasing the sensitivity of tumor cells to BH3 mimetic inhibitors." (PMID 39678489, 2024). "Conversely, overexpression of USP13 promoted xenografted tumor growth, size and weight in vivo." (PMID 37151889, 2023). "Also, we analyzed USP13 mRNA expression in forty paired tumor specimens and corresponding adjacent normal tissues by qRT-PCR, and our findings further confirmed the upregulation of USP13 mRNA level in OS." (PMID 37151889, 2023). "USP13 is a member of the DUBs family and plays key roles in various biological processes including tumor promotion, inflammation, apoptosis, drug resistance and anti-viral responses by cleaving ubiquitin molecules from associated proteins including STING, Myc, PTEN and Mcl-1." (PMID 36915206, 2023). "In addition, METTL3 ubiquitination level was reduced in tumor tissues which highly expressed USP13 compared to adjacent normal tissues." (PMID 37151889, 2023). "Consistently, knockdown or pharmacological inhibition of USP13 antagonized tumor cell growth." (PMID 35445009, 2022). "In addition to its oncogenic roles, USP13 exerts a tumor-suppressive role by deubiquitinating PTEN in different types of cancers." (PMID 36385557, 2022).